CDKN2A (cyclin dependent kinase inhibitor 2A)
Diseases named in the same sentence as CDKN2A in open-access papers (continued):
Sharing a sentence is not in itself a finding about the gene and the disease.
retinoblastoma (24 papers, 2003 to 2025). A malignant tumor that originates in the nuclear layer of the retina. "The proteins encoded by the CDKN2A/B genes belong to the INK4 family of CDK inhibitors, which block the ability of the tandem cyclin D-CDK4/CDK6 kinases to inactivate Retinoblastoma (RB) growth-suppressive functions." (PMID 33435487, 2021). "RB1, STAT3, and CDKN2A are the most likely core targets of curcumin for retinoblastoma treatment." (PMID 35911143, 2022). "Genome-wide profiling further reveals dozens of hypermethylated tumor suppressors (e.g., RB1, CDKN2A, RASSF1A, MLH1, etc.), reinforcing the idea of epigenetic cooperativity in retinoblastoma pathogenesis." (PMID 41150792, 2025). "In conclusion, this comprehensive network-based pharmacological analysis suggests a number of testable speculations on the potential molecular mechanisms of curcumin in the treatment of retinoblastoma and predicts RB1, STAT3, and CDKN2A as potential therapeutic targets." (PMID 35911143, 2022).
neuroblastoma (22 papers, 2004 to 2024). Neuroblastoma (NB) is the most common solid, extracranial childhood tumor. "CAI2 (CDKN2A/ARF Intron 2 lncRNA) is another neuroblastoma associated lncRNA located at the chromosomal locus 9p21, which harbors the well-known tumor suppressor genes CDKN2A and ARF." (PMID 26087192, 2015). "Aberrant activation of the MDM2 oncogene by gene amplification or inactivation of its inhibitory regulator CDKN2A occurs in 36.6% of primary neuroblastomas." (PMID 29416773, 2018). "HSV-1 miR-H4-5p directly targets cyclin-dependent kinase inhibitor 2A (p16) mRNA in neuroblastoma cell lines." (PMID 28769892, 2017). "Chromosome 9p, especially the gene CDKN2A, is subject to homozygous (four cases) and heterozygous deletions (five cases) in neuroblastoma tumors." (PMID 18664255, 2008). "Although alterations of the CDKN2A gene have been reported in many malignancies, it is a rare event in neuroblastoma (NB)." (PMID 15305192, 2004).
urothelial carcinoma (22 papers, 2011 to 2026). A malignant neoplasm derived from the transitional epithelium of the urinary tract (urinary bladder, ureter, urethra, or renal pelvis). "CDKN2A genomic alterations were associated with urothelial carcinoma treated with immune checkpoint inhibitors (ICIs)." (PMID 37287976, 2023). "Especially the copy number loss of CDKN2A in all models histologically classified as urothelial carcinoma (4/5 models) is in concordance with the TCGA data where 47% of non-squamous tumors exhibit this specific alteration." (PMID 26041878, 2015). "The somatic alterations were consistent with previous reports of urothelial carcinoma, including homozygous deletions of CDKN2A and CDKN2B." (PMID 41800036, 2026). "On the contrary, CDKN2A ALT was associated with poor response to ICIs and OS in 44 urothelial carcinoma patients treated with ICIs from the dana-farber cancer institute." (PMID 38822443, 2024). "Deletion of CDKN2A/CDKN2B genes in urothelial carcinoma were found to be a common event and have been shown to be a crucial event in the progression from normal urothelium to carcinoma." (PMID 34127009, 2021). "However, CDKN2A alterations were recently reported to be associated with reduced benefit from ICI therapy in urothelial carcinoma, but not with ICI outcomes for RCC." (PMID 36275737, 2022). "Taken together, our findings indicate that this CDKN2A alteration-mediated pathway represents a rational and novel therapeutic strategy target for CDC, even for all urothelial carcinomas, which needs further validation in patients." (PMID 34980126, 2022). "A previous study pointed out that genetic alteration of CDKN2A was correlated with reduced benefits from ICTs and changes in the TME of urothelial carcinoma." (PMID 35979371, 2022).
adenoma (21 papers, 2008 to 2026). A neoplasm arising from the epithelium. "CDKN2A is rarely methylated in GH and ACTH adenomas, and instead shows higher levels of mutations and LOH at the CDKN2A locus in prolactinoma and nonfunctional subtypes (p<0.002)." (PMID 24367530, 2013). "Moreover, MMR-deficient adenomas with a high grade of dysplasia revealed hypermethylation in four other genes, IGF2, CRABP1, NEUROG1, and CDKN2A." (PMID 34201893, 2021). "Throughout the process of gastric carcinogenesis, the frequency of CDKN2A methylation increases significantly, ranging from noncancerous dysplasia (4%) or adenoma (18%) to cancer‐associated dysplasia or adenoma (29%), ultimately leading to the development of gastric adenocarcinoma (44%)." (PMID 39184862, 2024). "In contrast to previous studies, we found hypermethylation of cyclin dependent kinase inhibitors - CDKN2A and CDKN2B in about half of the adenomas." (PMID 28600574, 2017). "ADAMTS1, CDKN2A, CRABP1, MLH1, NR3C1, RUNX3, and SCGB3A1 showed increasing methylation frequencies from adenomas to carcinomas, while HOXA9, MAL, and MGMT displayed overall equal methylation frequencies in all tumor subgroups." (PMID 19117505, 2008). "Moreover, Maki-Nevala and colleagues found higher methylation levels in four CIMP marker genes, namely NEUROG1, CDKN2A, IGF2, and CRABP1, in MMR-proficient adenomas compared to normal mucosa." (PMID 34201893, 2021). "Methylation of the CpG island of CDKN2A was detected in 32/46 (70%) non-secreting adenomas, in contrast to 2/21 (9.5%) somatotroph adenomas and 0/15 histologically normal postmortem pituitaries." (PMID 33574795, 2020). "Although the expression was reduced in approximately 85% of the adenomas, hypermethylation of CKDN2A and CDKN2B promoter regions was found in a much smaller proportion implying that other mechanism may be involved in CDKN2A and CDKN2Breduced expressions." (PMID 28600574, 2017). "Correlation analysis revealed that promoter methylation of CDKN2A was inversely related to adenoma weight (ρ = −0.48; p = 0.046), but not with clinico-pathological features of the patients." (PMID 28600574, 2017). "In addition, the promoter regions of CDKN2A, CDKN2B, and of RASSF1A were significantly hyper-methylated in 50% (n = 15), 47% (n = 14), and 90% (n = 27) of adenomas respectively." (PMID 28600574, 2017). "Finally, several other genes show decreased methylation in specific histopathological PA subtypes, including CDKN2A in GH and ACTH adenomas, RASSF1A in FSH/LH adenomas, and p27 in ACTH adenomas." (PMID 24367530, 2013). "Our previous studies of human samples and of a mouse model have revealed that serrated polyps and adenomas display high expression of the CDK inhibitor p16INK4a, a characteristic mark for senescence, which is lost in invasive carcinomas by CDKN2A promoter hypermethylation." (PMID 23045412, 2012). "Furthermore, cyclin-dependent kinase inhibitor 2A (CDKN2A) is a tumor suppressor and regulates the cell cycle; however, both genes are featured in the tumorigenesis of nonfunctioning adenomas and somatotroph adenomas." (PMID 40299639, 2025). "The MGMT, CDKN2A, and MLH-1 genes were methylated in 48%, 31%, and 0% of adenomas and 16%, 27%, and 10% of those with no detectable pathologies." (PMID 22969796, 2012).
glaucoma (21 papers, 2012 to 2025). Increased pressure in the eyeball due to obstruction of the outflow of aqueous humor. "By carrying out the search as described in the Section 2 first for CDKN2A, we generated a list of 38 GWAS gene variants which were statistically associated with the glaucoma phenotype." (PMID 40722690, 2025). "CDKN2B/CDKN2A encodes tumor suppressor proteins p16INK4A/p15INK4B which influences cell proliferation/senescence in RGCs, the degeneration of which is a risk factor for glaucoma." (PMID 33397358, 2021). "Background/Objectives: The INK4 locus at chromosome 9p21.3, encoding CDKN2A, CDKN2B and the long non-coding RNA CDKN2B-AS1 (ANRIL), has been implicated in multiple diseases, including glaucoma and cardiovascular disease." (PMID 40722690, 2025). "These epigenetic changes suppress the transcription of nearby tumour-suppressor genes CDKN2A and CDKN2B, thereby linking upstream signals to downstream cell cycle and stress response pathways relevant to both glaucoma and CVD." (PMID 40722690, 2025). "Thus, it is suggested that the variants in this gene would probably affect the expression level of the downstream genes CDKN2A and CDKN2B, which is response to the elevated IOP in glaucoma." (PMID 34648117, 2022). "CDKN2BAS also regulates the expression of CDKN2A, a gene previously shown to be down-regulated in other neurodegenerative disorders, including Alzheimer's disease, suggesting that regulation of CDKN2A expression by CDKN2BAS could also contribute to degeneration of the optic nerve in glaucoma." (PMID 22570617, 2012).
malignant mesothelioma (21 papers, 2011 to 2025). A malignant neoplasm of the pleura or peritoneum, arising from mesothelial cells. "Combined mutations of BAP1, NF2, and CDKN2A are observed in about 34% of malignant mesothelioma, indicating the importance of these tumor suppressors in the disease pathogenesis." (PMID 35204459, 2022). "For malignant mesothelioma, CDKN2A deletion was reported to be potential diagnostic and prognostic marker." (PMID 31448219, 2019). "The loss of BAP1 and CDKN2A are genetic events shown to effectively differentiate between malignant mesothelioma and reactive mesothelial hyperplasia." (PMID 30060501, 2018). "A high correlation of MTAP immunohistochemical reactivity with CDKN2A homozygous deletion (as determined by FISH) was first reported in malignant mesothelioma with a sensitivity of 78% and specificity of 98%." (PMID 39117984, 2024). "A prior study using a monoclonal anti-MTAP primary antibody reported acceptable specificity and sensitivity for MTAP immunohistochemistry in detecting the CDKN2A homozygous deletion and diagnosis of malignant mesothelioma." (PMID 38994676, 2024). "After confirmation of the mesothelial lineage, BAP1 loss, CDKN2A homozygous deletion, and MTAP loss were the most specific markers for the diagnosis of malignant mesothelioma." (PMID 35205689, 2022). "Genome-wide sequencing analyses of malignant mesotheliomas have revealed frequently observed genomic aberrations such as loss of function mutation and/or copy number alterations/deletion of BAP1, SETD2, CDKN2A, and NF2." (PMID 32545767, 2020). "Deletion of CDKN2A is commonly assessed through fluorescence in-situ hybridization (FISH), which is widely used as a molecular diagnostic tool in malignant mesothelioma." (PMID 30060501, 2018). "Four of the samples were found to have homozygous deletions of CDKN2A, consistent with rates reported in malignant mesothelioma cells." (PMID 25952750, 2015). "Although neither BAP1 nor CDKN2A mutations provide absolute specificity in diagnosing malignant mesothelioma, they remain invaluable adjuncts for differentiating PM from benign pleural lesions and prognostic assessment." (PMID 40904706, 2025). "The combination of BAP1 loss and homozygous p16 (CDKN2A) deletion by FISH and/or MTAP loss has become a cornerstone for distinguishing malignant mesothelioma from reactive mesothelial proliferations, while EZH2 overexpression represents an additional promising marker." (PMID 41375066, 2025). "BAP1 and CDKN2A gene mutations do not have a 100% specificity for the diagnosis of malignant mesothelioma, but they can help distinguish MPM from benign pleural diseases." (PMID 37461124, 2023). "We next investigated the influence of the protein expression of BAP1, NF2, CDKN2A, and LAG3 on the malignant mesothelioma TIME." (PMID 38994676, 2024). "MTAP served as a surrogate marker for CDKN2A/B, as the MTAP gene, located at 9p21, is frequently codeleted with CDKN2A/B within distinct types of malignant mesothelioma." (PMID 38994676, 2024). "miRNA-615-3p dysregulates CDKN2A, NF2 and JUN in malignant mesothelioma and enhances the phagocytic capacity of splenic macrophages." (PMID 23387986, 2013). "The CDKN2A/ARF locus encompasses overlapping tumor suppressor genes p16(INK4A) and p14(ARF), which are frequently co-deleted in human malignant mesothelioma (MM)." (PMID 21526190, 2011). "Recent studies indicate that while a positive identification of CDKN2A deletion is consistent with malignant mesothelioma, the lack of deletion does not preclude disease diagnosis." (PMID 30060501, 2018). "To clarify whether FISH or qPCR is the more sensitive approach for an adequate detection of selected deletion regions in FFPE tissues, we used six malignant mesothelioma (MM) FFPE samples, since MM have been shown to harbor CDKN2A-deletions in 25–50% of cases." (PMID 24733537, 2014).
malignant mesothelioma (continued). "Knockout mice with targeted deletion of specific Cdkn2A/Arf exons have disrupted p16Ink4a, p19Arf or both genes and develop a different spectrum of spontaneous tumors, although not malignant mesotheliomas (MMs)." (PMID 21526190, 2011). "Indeed, our most important finding is the lack of alterations involving BAP1, SETD2, NF2, CDKN2A, PBRM1, and SMARCC1 genes consistently mutated or deleted in malignant mesotheliomas." (PMID 32545767, 2020). "The WDPMs lacked the alterations involving BAP1, SETD2, NF2, CDKN2A/B, LASTS1/2, PBRM1, and SMARCC1 that are frequently found in malignant mesotheliomas." (PMID 32545767, 2020).
B-cell lymphomas (20 papers, 2006 to 2025). "When CD1d deficiency abrogated NKT2-B1a cell interactions and B1 B cell lymphoma strongly increased in these animals, one reason may be the Cdkn2a gene difference in the BALB/c background, which has the potential to strongly promote B1 B cell growth." (PMID 36050343, 2022). "Of note, other representative genes of B‐cell lymphoma, such as Cdkn2a and Pkm, Ldha, mirrored the expression profiles observed in thymic T‐cell lymphomas." (PMID 40887856, 2025). "CDKN2A homozygous deletion is a poor prognostic biomarker in B-cell lymphomas in general and has also been reported to be a common molecular abnormality in the PCNSLs of older patients." (PMID 38730692, 2024). "While CDKN2A deleterious alterations (highly recurrent in B cell lymphomas) have been shown to recur in systemic T cell lymphomas, our patient had a neutral copy number for this gene." (PMID 34198843, 2021). "Transcriptional silencing due to hypermethylation of CDKN2A is one of the major mechanisms involved in the pathogenesis of several types of malignancies such as B cell lymphoma, hepatocellular, lung and colorectal cancers." (PMID 28600574, 2017).
esophageal adenocarcinoma (20 papers, 2006 to 2026). A malignant tumor with glandular differentiation arising predominantly from Barrett mucosa in the lower third of the esophagus. "In another separate study, CDKN2A rs3088440 polymorphism was associated with reduced risk of progression from Barrett's esophagus to esophageal adenocarcinoma." (PMID 28445979, 2017). "Point mutations in Barrett esophagus and esophageal adenocarcinoma are relatively uncommon, but 9p loh and promoter hypermethylation appear to be frequent mechanisms of CDKN2A inactivation 117,118." (PMID 17576439, 2006). "Mutations in p16/CDKN2a detected in patients with Barrett's esophagus." (PMID 19043591, 2008). "Adenomatous Polyposis Coli (APC) promoter methylation is a characteristic of gastrointestinal cancers, and hypermethylation of the CDKN2A/p16 promoter leads to its inactivation in esophageal adenocarcinoma." (PMID 41150792, 2025). "CDKN2A is a tumor suppressor located in chromosome 9p21 and frequently lost in Barrett’s esophagus (BE) and esophageal adenocarcinoma (EAC)." (PMID 39753721, 2025). "CDKN2A (48%) was the most frequently inactivated tumor suppressor gene by altered methylation in EAC, but CDKN2A gene alterations at this moment are mainly investigated as a marker for progression to EAC in Barrett’s esophagus." (PMID 34638363, 2021).